NSUN2 (NOP2/Sun RNA methyltransferase 2)
Diseases named in the same sentence as NSUN2 in open-access papers (continued):
Sharing a sentence is not in itself a finding about the gene and the disease.
preeclampsia (1 paper, 2025). Preeclampsia is a hypertensive disorder of pregnancy that is characterized by new-onset hypertension with proteinuria presenting after 20 weeks of gestation, and depending on mild or severe forms may initially present with severe headache, visual disturbances, and hyperreflexia. "Using uterine eQTL data as a proxy for maternal contributions, we found that higher genetically predicted expression of CDC25A and NSUN2 was associated with decreased odds of preeclampsia." (PMID 41220585, 2025). "After outliers removal, the expressions of ATG16L1, PMVK and NSUN2 were found to be associated with odds of preeclampsia via the IVW method." (PMID 41220585, 2025). "However, none of these signals were confirmed in the replication dataset, with the only significant signal NSUN2 exhibiting an inverse association with preeclampsia." (PMID 41220585, 2025). "Our findings implicate several genes operating through diverse pathways—including ATG16L1, MAP3K14, PMVK, CDC25A, and NSUN2—as potential mediators linking senescence processes to odds of preeclampsia." (PMID 41220585, 2025). "Pleiotropy was observed in the association between NSUN2, ATG16L1 and preeclampsia in the replication dataset as suggested by MR-Egger analysis." (PMID 41220585, 2025). "Ultimately, functional studies in relevant cell and animal models are essential to confirm the causal impact of ATG16L1, PMVK, MAP3K14, NSUN2, and CDC25A on senescence phenotypes and preeclampsia pathogenesis." (PMID 41220585, 2025). "Synthesizing these results, dysregulation across interconnected pathways—autophagy (ATG16L1), inflammation (MAP3K14), metabolism (PMVK), cell cycle (CDC25A), and RNA methylation (NSUN2)—appears to converge on promoting placental cellular senescence, contributing to preeclampsia pathophysiology." (PMID 41220585, 2025). "Collectively, these findings suggest that disruptions in placental cell cycle control (CDC25A) and RNA modification pathways (NSUN2) may contribute significantly to preeclampsia pathology." (PMID 41220585, 2025). "These preliminary experimental findings lend support to the potential relevance of ATG16L1, PMVK, MAP3K14, NSUN2, and CDC25A dysregulation in preeclampsia pathophysiology." (PMID 41220585, 2025). "Key genes (ATG16L1, PMVK, MAP3K14, NSUN2, CDC25A) link cellular senescence to preeclampsia, offering insights for mechanistic studies and therapeutic targeting." (PMID 41220585, 2025). "Placental RT-PCR showed upregulated ATG16L1 and downregulated PMVK, MAP3K14, NSUN2, and CDC25A in preeclampsia." (PMID 41220585, 2025). "The results revealed that the expressions of ATG16L1, NSUN2 and PMVK were significantly downregulated in placental tissues from preeclampsia patients, whereas other key genes such as CDC25A and MAP3K14 did not vary significantly between groups." (PMID 41220585, 2025). "In conclusion, this multi-omics MR study, combined with preliminary experimental insights, pinpoints ATG16L1, PMVK, MAP3K14, NSUN2, and CDC25A as key candidate genes potentially mediating the link between cellular senescence pathways and odds of preeclampsia." (PMID 41220585, 2025).
prostate adenocarcinoma (1 paper, 2022). "Also, in the TCGA prostate adenocarcinoma (PRAD) cohort, NSUN2 was the most abundant gene among the cytosine‐5‐methyltransferases in PCa." (PMID 36169095, 2022).
pulpitis (1 paper, 2026). Inflammation of the dental pulp. "Nsun2 deficient mice showed significantly reduced inflammatory response in the models of systemic inflammation and local pulpitis compared with wild-type control mice." (PMID 41707999, 2026).
rectal adenocarcinoma (1 paper, 2025). "To evaluate the expression of NSUN2 in human tumour tissues, we noted that NSUN2 was highly expressed in the majority of solid tumours, including colon and rectal adenocarcinoma through TCGA pan‐cancer analysis." (PMID 40156167, 2025).
renal cell carcinoma (1 paper, 2025). "NOP2, NSUN2, and NSUN5 mRNA were significantly upregulated in renal cell carcinoma cell lines (786-O, Caki-1) compared to a human tubular epithelial immortalized cell line (HK-2), while NSUN4 was downregulated in the renal carcinoma cell lines." (PMID 41462962, 2025). "Furthermore, NOP2, NSUN2, and NSUN5 mRNA were significantly upregulated in renal cell carcinoma tissue, while NSUN4 mRNA was downregulated." (PMID 41462962, 2025).
rheumatoid arthritis (1 paper, 2025). A chronic, systemic autoimmune disorder characterized by inflammation in the synovial membranes and articular surfaces. "Compared with the normal control group, NSUN2 expression was significantly increased in rheumatoid arthritis patients and collagen-induced arthritis rats." (PMID 41462962, 2025). "Knocking down NSUN2 blocked the Wnt–β-catenin signaling pathway and inhibited pathological factors such as MMP3, fibronectin, and interleukins in rheumatoid arthritis." (PMID 41462962, 2025).
sarcoma (1 paper, 2023). A usually aggressive malignant neoplasm of the soft tissue or bone. "NSUN2 and NSUN7 were positively correlated with DDR1 expression in BLCA, HNSC, LIHC, sarcoma (SARC), THCA, and thymoma (THYM)." (PMID 37031216, 2023).
Stroke (1 paper, 2025). Sudden impairment of blood flow to a part of the brain due to occlusion or rupture of an artery to the brain. "Pharmacological inhibition of lactate production or knockdown of NSUN2 attenuated the release of pro-inflammatory cytokines and reduced cerebral injury, underscoring the central role of the lactate-H3K18la-NSUN2 axis in mediating post-stroke neuroinflammation." (PMID 41585085, 2025).
tauopathies (1 paper, 2023). "First, while we were able to analyze the effects on NSun2 expression in neurons, future studies should explore possible NSun2 dysregulation and any effects on cellular pathology in glial cells in the context of AD and other tauopathies." (PMID 36357715, 2023). "Unexpectedly, our results also show that NSun2 protein is not reduced in primary tauopathies like PART and PSP, indicating a distinct NSun2-related disease mechanism in the AD brains." (PMID 36357715, 2023).
vascular sclerosis (1 paper, 2025). "Moreover, donor NSUN2 deficiency hindered the development of allograft arteriosclerosis in vivo." (PMID 41583468, 2025). "Intercellular adhesion molecule 1 (ICAM-1), a crucial factor in upregulating endothelial inflammation and vascular sclerosis, has been reported to be regulated by NSUN2-mediated m5C mRNA methylation." (PMID 41583468, 2025).
tumor (131 papers, 2016 to 2026). "Functionally, loss of NSUN2 catalytic activity impaired tumor-cell migration, invasion, and DRG neurite outgrowth, as shown in transwell and co-culture assays." (PMID 41356184, 2026). "Glucose, through the modulation of NSUN2 activity, exerts influence over global m5C RNA methylation and the accumulation of membrane‐associated DNA, ultimately fostering tumour development and immune therapy resistance." (PMID 40008496, 2025). "High NSUN2 expression is generally associated with advanced tumor stage, enhanced tumor invasiveness, increased metastatic risk, and predicts reduced overall survival (OS) and progression-free survival (PFS)." (PMID 41256859, 2025). "NSUN2 serves as the primary writer for m5C RNA methylation, and its aberrant expression or mutation is closely associated with tumor initiation and progression." (PMID 40765828, 2025). "In summary, NSUN2 exerts a central role in invasion and metastasis across multiple tumor types through m5C modification and associated downstream gene axes." (PMID 41256859, 2025). "As anticipated, metabolically suppressed or NSUN2-deficient tumor cells exhibited a markedly diminished capacity to inhibit the antitumor functions of CD8+ T cells compared to control tumor cells." (PMID 40765828, 2025). "Overexpression of NSUN2 leads to gefitinib resistance and tumor recurrence, while genetic inhibition of NSUN2 causes tumor regression and overcomes the intrinsic resistance to gefitinib both in vitro and in vivo." (PMID 40919129, 2025). "For instance, in ESCC, elevated NSUN2 levels are associated with advanced tumor stages and reduced patient survival, emphasizing its potential as a prognostic marker." (PMID 40114967, 2025). "The clinicopathological correlation analysis revealed that the NSUN2 expression level was significantly associated with the tumor size and TNM stage of CRC." (PMID 38769664, 2024). "For example, in mouse tumour models, NSUN2 deficiency increases the sensitivity of tumour cells to 5‐Fu and CDDP drugs." (PMID 38572667, 2024). "In vivo assays also showed that forced expression of E2F1 reversed the suppression of tumor growth and metastasis induced by NSUN2 deficiency." (PMID 38424195, 2024). "To further demonstrate the function of signalling cascade of NSUN2‐PFAS in the tumorigenesis of RB, we have tested the tumour proliferative ability in the orthotopic xenograft model by reintroducing PFAS in NSUN2‐deficient cells." (PMID 37228185, 2023). "Among them, NSUN2 is the target of the proto-oncogene c-Myc, which is most closely linked to tumor development and most likely to be involved in the formation of chemotherapy drug resistance." (PMID 36437944, 2022). "We compared the expression of NSUN2 in 51 pairs of tumor and adjacent paired samples through the TCGA database, and found that NSUN2 was upregulated in tumors and associated with higher tumor stage and biochemical recurrence risk." (PMID 35978830, 2022). "The NSUN family member, NSUN2, is found to be implicated in regulating cell cycles and accumulates in a variety of tumor lesions compared with normal samples." (PMID 33912441, 2021). "Consistently, the in vivo orthotopic tumor xenograft results also confirmed that NSUN2 deficiency suppressed HCC growth in nude mice." (PMID 32978516, 2020). "Additionally, NSUN2 overexpression led to gefitinib resistance and tumor recurrence, while NSUN2 gene inhibition caused tumor shrinkage in vitro and in vivo and overcame intrinsic resistance to gefitinib." (PMID 41462962, 2025). "Furthermore, NSUN2 upregulation is closely associated with chemotherapeutic resistance in multiple tumor types." (PMID 41256859, 2025). "Additionally, 3-MA treatment partially restored tumor growth in shNSUN2 cells, indicating autophagy is critical for NSUN2 loss-induced tumor suppression." (PMID 41436732, 2025). "Notably, smaller and lighter tumours formed within the eyeball in the NSUN2‐deficient group than in the empty vector group." (PMID 37228185, 2023).
tumor (continued). "We found that the levels of infiltrating immune cells in 35 tumor types were significantly associated with NSUN2 expression, and the expression of NSUN2 was highly related to B cells, macrophages, CD4 T cells, neutrophils, CD8 T cells and dendritic cells (DCs) and most related to neutrophils." (PMID 37769000, 2023). "The results revealed that the high expression of NSUN2 is associated with the prognosis of different tumor types and pathological stages of tumors, suggesting that NSUN2 might serve as a poor prognostic factor in cancers." (PMID 37769000, 2023). "Integration of RNA-BisSeq and RNA-seq in UCB cell and tumor samples, we found that the m5C level of NSUN2 mRNA was positively associated with NSUN2 mRNA expression in SYSUCC cohort, suggesting that NSUN2 expression is regulated by its mRNA m5C methylation level." (PMID 36806253, 2023). "NSUN2 expression is closely associated with tumor prognosis." (PMID 35978830, 2022). "In cutaneous squamous cell carcinoma, the reduced rate of protein synthesis may be caused by the low expression of NSUN2, which results in certain stem cell characteristics of tumor initiating cells." (PMID 35371346, 2022). "Currently, published data have shown that NSUN2 is overexpressed in various tumors, such as breast cancer, colorectal cancer, and gallbladder carcinoma, and is associated with a series of malignant phenotypes such as tumor proliferation and migration." (PMID 35574373, 2022). "Importantly, the data showed that Nsun2 deficiency in cells blocked them in an undifferentiated and more proliferative state necessary for the self-renewal of tissue or tumour stem cells." (PMID 33461542, 2021). "The close association of NSUN2 with tumor features suggests that it may be a key factor in the study of the relationship between RNA m5C modification and tumorigenesis." (PMID 32978516, 2020). "The expression of NSun2 is closely associated with tumor development and prognosis." (PMID 33093178, 2020). "Detailed analyses demonstrated that the expression of NSUN2 is significantly associated with clinical stage (P=0.021), tumor (T) classification (P=0.012), pathological differentiation (P=0.023), ER status (P<0.001), PR status (P=0.001), and Ki-67 expression level (P=0.008)." (PMID 27447970, 2017). "NSUN2 deficiency may inhibit cellular processes and tumor growth in HCC by suppressing FZR1." (PMID 41462962, 2025). "To further explore the tumor-promoting role of NSUN2 dependently on m5C modification in CC, we constructed a wide-type NSUN2 expression plasmid (NSUN2-WT) and an m5C methyltransferase-mutated plasmid (NSUN2-MUT) by introducing point mutations in releasing and catalytic sites (cysteine 271 and 321)." (PMID 36632452, 2023). "Furthermore, higher NSUN2 RNA was significantly associated with advanced ESCC tumor stage." (PMID 34345012, 2021). "In skin cancer, loss of NSUN2 expression was correlated with increased malignancy when protein expression levels in normal skin and cutaneous cancers were compared across increasing tumor/node/metastasis (TNM) stages and was associated with an increase of tumor-initiating cells." (PMID 32708015, 2020). "Integrated analysis of RNA sequencing and NSUN2 RIP-seq identified several candidate target genes (including STC1, CDCP1, FOSL1, and Serpine1) associated with tumor invasion and neuronal interactions 22-25." (PMID 41356184, 2026). "In anaplastic thyroid carcinoma, upregulation of the tRNA m5C methyltransferase NSUN2 correlates with tumor dedifferentiation and aggressiveness." (PMID 41362736, 2026). "Pathway enrichment analysis of NSUN2-bound transcripts similarly highlighted signaling programs related to tumor invasion and neuronal interactions." (PMID 41356184, 2026). "Functionally, inhibiting lactylation or blocking NSUN2 markedly attenuated tumor-nerve interactions and neural invasion." (PMID 41356184, 2026).
tumor (continued). "The RNA cytosine-5 methyltransferase NSUN2 is an emerging therapeutic target in precision oncology, with aberrant overexpression driving tumor progression, metastasis, and therapy resistance across multiple malignancies." (PMID 41617787, 2026). "In situ AAV-mediated delivery of shNSUN2 efficiently silenced NSUN2 expression, as verified by both qPCR and immunofluorescence quantification of tumor tissues." (PMID 41356184, 2026). "NSUN2 mediates m5C modifications to regulate the expression of key metabolic enzymes and immune-related genes, thereby promoting tumor cell proliferation, migration, stemness maintenance, and immune evasion." (PMID 41256859, 2025). "As an RNA m5C methyltransferase, NSUN2 not only regulates intrinsic tumor cell proliferation and metabolism but also significantly modulates the immune state of the tumor microenvironment through regulation of immune-related genes and molecules." (PMID 41256859, 2025). "Given its multifaceted roles in tumor initiation, proliferation, metastasis, and drug resistance, NSUN2 serves not only as a potential biomarker but also as a candidate target for therapy." (PMID 41256859, 2025). "Mechanistically, glucose metabolic dominance triggers NSUN2 upregulation in tumor cells, where this functional RNA methyltransferase stabilizes key glycolytic transcripts (GLUT1, HK2, PFKM) through mRNA methylation." (PMID 40765828, 2025). "Collectively, these findings identify NSUN2 as a potential glucose sensor, highlighting its critical role in driving tumor evolution." (PMID 40765828, 2025). "Beyond intrinsic tumor functions, NSUN2 also shapes the tumor immune microenvironment by regulating immune checkpoint molecules, cytokine networks, and immune cell activities, ultimately contributing to immune evasion and influencing immunotherapy efficacy." (PMID 41256859, 2025). "Overall, lactate-mediated lactylation of NSUN2 represents a critical PTM mechanism to regulate tumor cell survival under lactate stress." (PMID 39742570, 2025). "NSUN2 silencing inhibits PC cell proliferation, migration, and invasion, while reducing tumor growth and metastasis in vivo." (PMID 41256859, 2025). "We further validated the expression and subcellular localization of these hub proteins in tumor tissues by selectively performing IHC staining using antibodies against the NSUN2, TM9SF3 (transmembrane 9 superfamily member 3), and PKC (protein kinase C)." (PMID 39716938, 2025). "Recent studies have demonstrated that NSUN2 significantly influences the tumor immune microenvironment (TME) by regulating the expression of key immune-related genes through its RNA 5-methylcytosine (m5C) methyltransferase activity." (PMID 41256859, 2025). "IHC staining for NSUN2 in the CRC tissue microarrays revealed that NSUN2 protein levels were higher in CRC tumour tissues than in adjacent normal tissues." (PMID 40156167, 2025). "Hematoxylin and eosin (HE) staining confirmed successful tumor formation, and immunohistochemical (IHC) analysis verified NSUN2 depletion." (PMID 40083919, 2025). "Freshly CRC tissues were then collected and detected to reveal a notably increased expression of NSUN2 protein in CRC tumours compared with normal tissues." (PMID 40156167, 2025). "Overall, these findings reveal the glucose-competition/NSUN2 axis as a pivotal driver of tumor evolution and immune evasion, primarily through disrupting CD8+ T cell metabolism and suppressing their antitumor activity within the TIME." (PMID 40765828, 2025). "In CRC, m5C modification drives tumor metabolic reprogramming through the NSUN2/YBX1/m5C-ENO1 signaling axis, establishing a self-sustaining positive feedback loop." (PMID 41446042, 2025). "As an RNA 5-methylcytosine (m5C) methyltransferase, NSUN2/Nsun2 has emerged as an important regulator in various immune-modulatory processes and tumor progression." (PMID 41256859, 2025).